CRP (C-reactive protein)
Diseases named in the same sentence as CRP in open-access papers (continued):
Sharing a sentence is not in itself a finding about the gene and the disease.
Arterial stenosis (2 papers, 2023 to 2024). Narrowing or constriction of the inner surface (lumen) of an artery. "One study showed that serum hs-CRP levels were significantly higher in patients with moderate and severe arterial stenosis than in patients with mild stenosis." (PMID 36873405, 2023). "Analysis revealed that age, weight, BMI, CHA2DS2-VASc score, Killp classification, serum albumin, TG, Scr, eGFR, lymphocyte count, RBC, hemoglobin, Hs-CRP, BNP, PNI, LAD, LVEF, and left circumflex artery stenosis were statistically significant variables." (PMID 38562185, 2024).
arteriolosclerosis (2 papers, 2016 to 2022). The thickening of the wall of the small arteries and arterioles. "The top 8 variables with a higher ML score (GP) were body mass index (BMI), complement C3, serum total protein, arteriolosclerosis, urinary protein excretion during the 10-year follow-up, edema, C-reactive protein, and the Oxford E1 score." (PMID 36351996, 2022). "Herein, the ML score (GP) for MaxGD ≥ 242.3 μm identified the top 8 variables, including BMI, complement C3, serum total protein, arteriolosclerosis, urinary protein excretion (U-Prot) during the 10-year follow-up, edema, C-reactive protein, and the Oxford E1 score." (PMID 36351996, 2022).
aseptic loosening (2 papers, 2022). A failure of the bond between an implant and bone in the absence of infection. "The sensitivity and specificity of ESR and CRP in distinguishing aseptic loosening from PJI were also included." (PMID 35626351, 2022).
atopic asthma (2 papers, 2017 to 2026). An asthma that is characterized by symptoms that are triggered by an allergic reaction caused by inhaled allergens such as dust mite allergen, pet dander, pollen and mold. "A direct correlation between SCF, IL-31 and FEV-1/ FVC %, CRP and wheezing existed and suggested that both SCF and IL-31 play an important role in mediating inflammation and enhancing severity of atopic asthma." (PMID 28100228, 2017).
autoimmune myocarditis (2 papers, 2023 to 2025). Autoimmune myocarditis is an autoimmune disease that affects the heart. "Also noteworthy is the observation that KD and MIS-C often share myocardial complications, including autoimmune myocarditis (AM), which is predicted by the high C-reactive protein (CRP) and troponin found in the blood samples of many patients." (PMID 36769320, 2023). "Similarly, autoimmune myocarditis was considered unlikely due to the absence of systemic inflammatory markers (CRP, ESR) and normal autoimmune panel results." (PMID 40870916, 2025).
autoimmune neurological diseases (2 papers, 2024 to 2026). "Systemic inflammation, indicated by elevated white blood cell count and CRP level in the patients’ blood, was highest in patients of both infectious groups and lowest in patients with autoimmune neurological diseases." (PMID 37656347, 2024).
autoimmune vasculitis (2 papers, 2024 to 2025). An autoimmune form of vasculitis. "Complete blood count, inflammatory marker such as C-reactive protein and autoimmune vasculitis antibodies were found to be normal." (PMID 39544304, 2024). "Additionally, both C-reactive protein and immune vasculitis assays returned negative results, effectively excluding autoimmune vasculitis and infection as potential etiological factors." (PMID 39544304, 2024).
avian influenza (2 papers, 2022 to 2023). Infection of domestic and wild fowl and other birds with influenza A virus. "The inflammatory response promotes abnormal liver function and leads to the production of CRP and D-dimer, which have also been identified as biomarkers of disease severity in SARS-CoV-2 and avian influenza." (PMID 36119044, 2022).
basal cell carcinoma (2 papers, 2022 to 2023). A carcinoma involving the basal cells. "Data on non-melanoma skin cancer in parallel with CRP seem to be in relatively short supply; some case reports reveal notable CRP increases in skin squamous cell and basal cell carcinoma patients, and a study has shown moderately elevated CRP values in cases with advanced Merkel cell carcinoma." (PMID 37873776, 2023).
Bell's palsy (2 papers, 2024 to 2025). Partial or complete paralysis of the facial muscles of one side of a person's face. "All patients in the subgroups with Bell’s palsy, idiopathic intracranial hypertension, and other diagnoses (n = 15) had a CRP concentration in the normal range." (PMID 38539395, 2024).
bipolar II disorder (2 papers, 2019 to 2023). A bipolar disorder that is characterized by at least one hypomanic episode and at least one major depressive episode; with this disorder, depressive episodes are more frequent and more intense than manic episodes. "Using high-sensitivity testing of fasting plasma CRP levels at baseline and after treatment, Chang and colleagues reported that a baseline CRP level of 621.6 ng/mL could discriminate between bipolar disorder II and MDD." (PMID 30995920, 2019). "The possible reason might be treatment effects as indicated by Chang’s work itself: the difference of CRP level would become narrower between MDD and bipolar II disorder after treatment." (PMID 37845658, 2023).
bladder disorder (2 papers, 2013 to 2014). "In our study, serum NGF and CRP levels were significantly increased in IC/BPS patients, suggesting that chronic inflammation is involved in this bladder disorder." (PMID 24146927, 2013).
brain cancer (2 papers, 2022 to 2025). A primary or metastatic malignant neoplasm affecting the brain. "Commonly used biomarkers such as clinical disease activity indices, C-reactive protein (CRP), and fecal calprotectin achieve suboptimal sensitivity and specificity for brain cancer diagnosis." (PMID 40761875, 2025).
C. perfringens infection (2 papers, 2022). "C. perfringens infection increased the concentrations or activities of LPS, IL-6, CRP, PCT and MPO, causing a systemic inflammatory response to broilers, while the supplement of EA in diet relieved these adverse effects." (PMID 35436978, 2022).
carbohydrate metabolism disorders (2 papers, 2020 to 2024). "All patients underwent transthoracic two-dimensional echocardiography with an assessment of standard indicators of systolic and diastolic cardiac function, global longitudinal strain (GLS), laboratory diagnostics of carbohydrate metabolism disorders markers, NT-proBNP, and CRP." (PMID 39335545, 2024).
central nervous system infection (2 papers, 2012 to 2025). "Diagnostic tests include blood count, reticulocytes, urinalysis, c-reactive protein, cultures, chest X-ray, and lumbar puncture if suspicion of central nervous system infection." (PMID 40850219, 2025).
cerebral malaria (2 papers, 2015 to 2018). A sequestration of Plasmodium falciparum in the brain, which can cause coma and/or seizures. "In the previous studies, the association of various plasma detectable markers (PCT, CRP, ICAM, ANG2, TNFα and IP-10) with mortality in patients with severe or cerebral malaria have been reported." (PMID 30286756, 2018).
cerebral microbleeds (2 papers, 2014 to 2021). Cerebral microbleeds are a group of pathological processes affecting the small arteries, arterioles, capillaries and venules of the brain, as detected by brain imaging techniques. "The relationship between CRP and ICH was further demonstrated by a study showing hs-CRP concentrations were associated with cerebral microbleeds, in both lobar and deep locations." (PMID 25191699, 2014).
Charcot arthropathy (2 papers, 2016 to 2024). "Blood tests (CRP levels) were only performed in a clinically suspicious situation, i.e., when a patient presented with redness and warmth of the foot, to discriminate infection from active Charcot arthropathy." (PMID 28031030, 2016).
cholecystolithiasis (2 papers, 2019 to 2023). Single or multiple, ovoid or irregular, solid particles that are formed from bile, cholesterol, and calcium in the gallbladder cavity. "Multivariate logistic regression analysis showed that CRP > 55 g/L, cholecystolithiasis, duration of disease >72 h were the independent risk factors associated with the failure in achieving CVS." (PMID 31358829, 2019).
chronic lower respiratory disease (2 papers, 2021 to 2022). "Aside from the results for chronic lower respiratory disease, controlling for CRP in the truncated dataset did not otherwise change the pattern or significance of these results." (PMID 36820240, 2022).
chronic myelomonocytic leukemia (2 papers, 2021 to 2023). A myelodysplastic/myeloproliferative neoplasm which is characterized by persistent monocytosis, absence of a Philadelphia chromosome and BCR/ABL fusion gene, fewer than 20 percent blasts in the bone marrow and blood, myelodysplasia, and absence of PDGFRA or PDGFRB rearrangement. "In a retrospective study, we analyzed the prevalence of elevated C‐reactive protein (CRP) serum levels in 148 patients with chronic myelomonocytic leukemia (CMML), their potential prognostic impact, and potential correlations with laboratory features." (PMID 36441359, 2023). "Using the database of the Austrian Biodatabase for Chronic Myelomonocytic Leukemia (ABCMML), we analyzed 148 CMML patients with available information on CRP values." (PMID 36441359, 2023).
chronic plantar fasciitis (2 papers, 2024). "In our cross-sectional study of 295 individuals presenting with foot or ankle pain, we observed a statistically significant association between plantar fasciitis and elevated CRP levels, suggesting systemic inflammation." (PMID 38983990, 2024). "This study explores the association between chronic plantar fasciitis and elevated C-reactive protein (CRP) levels in individuals with cardiovascular risk factors." (PMID 38983990, 2024). "Our study's novel finding is the association between plantar fasciitis and elevated CRP levels, which has yet to be conclusively established in the existing literature." (PMID 38983990, 2024). "Then, we conducted a chi-square test of independence to see if there was a statistically significant association between having plantar fasciitis and having a high CRP level." (PMID 38983990, 2024). "A statistically significant association was observed between plantar fasciitis and elevated CRP levels (p=0.035)." (PMID 38983990, 2024). "To analyze the association between plantar fasciitis and high CRP levels, we categorized CRP levels into a binary variable (high for values greater than 1 mg/L and non-high risk for values less than 1 mg/L)." (PMID 38983990, 2024). "We found a statistically significant association (p-value = 0.035) between having plantar fasciitis and having high CRP (>1)." (PMID 38983990, 2024). "This study investigates the potential correlation between chronic plantar fasciitis and cardiovascular disease risk, as indicated by elevated CRP levels." (PMID 38983990, 2024). "We will investigate whether chronic heel pain caused by plantar fasciitis correlates with elevated CRP levels, reflecting systemic inflammation." (PMID 38983990, 2024). "Also, interventional studies assessing the impact of treating plantar fasciitis on CRP levels and cardiovascular risk factors would provide insight into potential benefits beyond symptom relief." (PMID 38983990, 2024). "This condition of heightened CRP levels, more prevalent in those with plantar fasciitis, may suggest a heightened risk of cardiac issues." (PMID 38983990, 2024). "Elevated levels of CRP, associated with chronic plantar fasciitis, suggest a link to systemic inflammation, which could elevate the risk of CVD." (PMID 38983990, 2024). "The heightened CRP levels in individuals with plantar fasciitis, even when controlled for other cardiovascular risk factors, hint at the possibility that plantar fasciitis itself may be a marker of systemic inflammation and, therefore, a potential risk factor for cardiovascular disease." (PMID 38983990, 2024). "Longitudinal studies investigating the temporal relationship between the onset of plantar fasciitis, changes in CRP levels, and the development of cardiovascular events would be particularly interesting." (PMID 38983990, 2024). "We investigated the correlation between plantar fasciitis and elevated CRP levels, defined as >1 mg/L, in the context of cardiovascular risk assessment." (PMID 38983990, 2024). "The observed correlation between increased CRP levels and plantar fasciitis suggests that plantar fasciitis might be a clinical indicator of systemic inflammation and could improve the assessment of CVD risk." (PMID 38983990, 2024). "The direct connection between plantar fasciitis and increased CRP levels has not been conclusively established in existing literature." (PMID 38983990, 2024).
chronic rhinosinusitis (2 papers, 2024). Chronic form of sinusitis. "Furthermore, the EB group also had a higher rate of chronic rhinosinusitis (P < 0.05), serum total IgE level (P < 0.01), and high-sensitivity C-reactive protein (HS-CRP) level (P < 0.05)." (PMID 38228883, 2024).
cocaine abuse (2 papers, 2013 to 2015). Disorders related or resulting from use of cocaine. "Cocaine abuse also increases expression of acute phase proteins such as C-reactive protein (CRP) and serum amyloid A (SAA), which cause chronic inflammatory effects, including in the brain." (PMID 26539167, 2015).
cognition (2 papers, 2018 to 2022). Intellectual or mental process whereby an organism becomes aware of or obtains knowledge. "The potential mediating role of CRP in the ACEs-cognition decline association should be examined in further research." (PMID 35753000, 2022). "Increased CRP levels have been associated with a wide range of impaired cognitive functions." (PMID 30190688, 2018).
Cryptococcal meningitis (2 papers, 2022 to 2024). Meningeal inflammation produced by cryptococcus neoformans, an encapsulated yeast that tends to infect individuals with acquired immunodeficiency syndrome and other immunocompromised states. "Serum C-reactive protein (CRP) concentrations at baseline have been identified as a risk factor for death in persons presenting with symptomatic HIV-associated cryptococcal meningitis." (PMID 39086467, 2024). "In HIV-associated cryptococcal meningitis, baseline serum C-reactive protein (CRP) concentrations are positively associated with increased mortality." (PMID 39086467, 2024). "Although previously published data show that elevated baseline CRP is a risk factor for death among people with cryptococcal meningitis, it is unknown whether CRP similarly predicts progression to cryptococcal meningitis and/or death among asymptomatic CrAg-positive persons." (PMID 39086467, 2024). "Moreover, lenalidomide induces a sustained decrease in plasma IL-6, TNF-α, CRP, D-dimer, and CA-HIV-1 RNA from PBMCs in patients with HIV-associated cryptococcal meningitis." (PMID 35967862, 2022).
dental pulp inflammation (2 papers, 2025). "Specifically, this study seeks to fill the knowledge gap regarding the feasibility and diagnostic accuracy of CRP rapid POC testing in detecting dental pulp inflammation." (PMID 40410141, 2025). "We hypothesize that the CRP rapid POC test (Index test) may demonstrate potential diagnostic value in detecting dental pulp inflammation." (PMID 40410141, 2025). "This pilot study suggests that the CRP rapid POC test may have potential as a diagnostic aid for detecting dental pulp inflammation." (PMID 40410141, 2025). "The scientific rationale for evaluating CRP in this context stems from its ability to detect localized dental pulp inflammation." (PMID 40410141, 2025). "This pilot study explored the feasibility of using a CRP rapid POC test as a potential adjunctive tool for detecting dental pulp inflammation." (PMID 40410141, 2025). "The aim of this pilot study was to assess the feasibility of using a CRP rapid POC test as a potential diagnostic aid in distinguishing between reversible and irreversible pulpitis." (PMID 40410141, 2025). "This pilot study provides preliminary evidence supporting the feasibility of the CRP rapid POC test as a potential adjunctive tool for assessing dental pulp inflammation." (PMID 40410141, 2025). "This study explores the feasibility of using a rapid C-reactive protein (CRP) chairside point-of-care (POC) test as a potential adjunctive tool for detecting dental pulp inflammation." (PMID 40410141, 2025). "We hypothesized that pulpal blood hs-CRP concentrations would correlate strongly with pain severity and provide objective discrimination of irreversible pulpitis." (PMID 41573808, 2025). "By correlating CRP levels with clinical indicators such as pain history and percussion test results, we hypothesize that CRP testing can offer an objective measure of pulpitis severity." (PMID 40410141, 2025). "In contrast, among irreversible pulpitis cases, only 23.1% had negative CRP results, while 53.8% exhibited mild to moderate CRP levels, and 23.1% had severe CRP elevation (p = 0.033)." (PMID 40410141, 2025).
diabetic cardiomyopathy (2 papers, 2022 to 2024). Diabetic cardiomyopathy is a disorder of the heart muscle in people with diabetes. "Elevated inflammatory markers like CRP and TNF-α levels were observed in diabetic cardiomyopathy patients in line with our study." (PMID 39204151, 2024).
Diplopia (2 papers, 2025). Diplopia is a condition in which a single object is perceived as two images, it is also known as double vision. "At symptoms onset, he also had a concurrent episode of diplopia, jaw pain, and temporal scalp tenderness associated with CRP elevation of 208 mg/L." (PMID 40295291, 2025).
dirofilariasis (2 papers, 2017 to 2019). Infection with nematodes of the genus dirofilaria, usually in animals, especially dogs, but occasionally in humans. "Although further research is necessary, CRP and Hp have a potential prognostic role in dogs with dirofilariasis as increases in positive APP correlated with presence and severity of PH." (PMID 29143686, 2017). "CRP and Hp have a potential prognostic role in dogs with dirofilariasis because increases in positive APP correlated with presence and severity of PH." (PMID 29143686, 2017).
distal colitis (2 papers, 2017 to 2023). Particular variety of ulcerative colitis where only the left half of the colon is inflamed. "Thus, elevated levels of CRP and FC in patients with distal colitis may serve as potential markers to predict progression of the lesion." (PMID 37457023, 2023). "Inflammation, coagulation and immune indicators like CRP, FC, IL-10, D-D and α1-MG are higher in extensive colitis, and metabolic indicators like LDL-C, HDL-C, TC, GSP and albumin are higher in distal colitis." (PMID 37457023, 2023).
DRESS syndrome (2 papers, 2025). "CRP and PCT values ​​were found to be elevated in a retrospective observational study of 94 possible, probable and confirmed cases of DRESS syndrome, even when concomitant infection was excluded." (PMID 39521708, 2025). "Evaluating CRP and PCT values ​​in light of these results can help clinicians differentiate between cases of DRESS syndrome with and without concomitant infection, or other causes of inflammation." (PMID 39521708, 2025).